RNU2-12P (RNA, U2 small nuclear 12, pseudogene)
Gene: Small nuclear RNA gene on chromosome 1 (176,243,862 to 176,244,029, reverse strand). Ensembl gene ENSG00000253025.
Homologues: Orthologues: chimpanzee U2 (100% identical), pig U2 (39% identical), rabbit U2 (39% identical), macaque U2 (35% identical), macaque U2 (34% identical), macaque U2 (31% identical), dog U2 (30% identical). Paralogues in human: RNU2-10P (44% identical), RNU2-22P (43% identical), RNU2-41P (39% identical), RNU2-34P (39% identical), RNU2-60P (37% identical), RNU2-16P (36% identical), RNU2-55P (36% identical), RNU2-58P (36% identical), RNU2-72P (36% identical), RNU2-28P (36% identical), RNU2-35P (36% identical), RNU2-24P (35% identical), and 62 more.